VCP (valosin containing protein)
Diseases named in the same sentence as VCP in open-access papers (continued):
Sharing a sentence is not in itself a finding about the gene and the disease.
non-small cell lung carcinoma (10 papers, 2011 to 2025). A group of at least three distinct histological types of lung cancer, including non-small cell squamous cell carcinoma, adenocarcinoma, and large cell carcinoma. "In non-small cell lung carcinoma, VCP interacts with MEST, leading to NF-kB pathway activation, promoting tumor invasion and metastasis." (PMID 39802400, 2025). "Recently, several studies reported that VCP is overexpressed in certain tumor types and associated with poor prognosis, including HCC, gastric cancer, and non-small cell lung carcinoma (NSCLC)." (PMID 35562734, 2022). "A recent study indicated that VCP expression levels are correlated with prognosis and progression of non-small cell lung carcinoma (NSCLC)." (PMID 22216170, 2011). "A previous clinical study has indicated that elevated VCP protein expression is a prognosticator for overall survival in both early and advanced pathologic stages (pT) of non-small cell lung carcinoma (NSCLC)." (PMID 22216170, 2011). "Our results show that VCP is significantly overexpressed in non-small cell lung carcinoma (NSCLC) as compared to normal tissues and cell lines (p<0.001)." (PMID 22216170, 2011). "Recent studies have also indicated that VCP expression may be an independent prognostic factor for overall survival in non-small cell lung carcinoma." (PMID 27344168, 2016). "Hence, the primary aim of this study was to evaluate the in vitro efficacy of dendrimer-encapsulated potent VCP-inhibitor drug in controlling non-small cell lung carcinoma (NSCLC) progression." (PMID 27434122, 2016). "Therefore, this study utilizes a dendrimer encapsulating a potent VCP-inhibitor, DBeQ, to provide a targeted and sustained drug delivery to the non-small cell lung carcinoma cells (NSCLC)." (PMID 27434122, 2016). "VCP/p97 overexpression has also been detected in tissues from patients with non-small cell lung carcinoma (NSCLC)." (PMID 34576340, 2021). "Elevated valosin containing protein (VCP/p97) levels promote the progression of non-small cell lung carcinoma (NSCLC)." (PMID 27434122, 2016). "Recent studies have also indicated that VCP expression may be an independent prognostic factor for overall survival in non-small cell lung carcinoma (NSCLC)." (PMID 22216170, 2011).
prostate carcinoma (10 papers, 2012 to 2024). A carcinoma that arises from epithelial cells of the prostate gland. "VCP (valosin-containing protein) is crucial for maintaining mitochondrial function, and in prostate cancer cells, it employs self-aggregation to inhibit mitochondrial activity, thereby evading cell death during nutrient deprivation and promoting malignancy." (PMID 38167084, 2024). "VCP is reported to involve in multiple disease states including neurodegenerative disorders and several tumor types such as squamous cell carcinoma and prostate cancer." (PMID 35562734, 2022). "Specifically, VCP/p97 expression was evaluated using immunohistochemistry and transcriptome analyses in 136 patients with prostate cancer treated with conservative therapy, such as radiation, watchful waiting and androgen deprivation." (PMID 34576340, 2021). "Increased serum VCP levels were observed in the majority of cancer cases, with the exception of patients with lung or prostate cancer." (PMID 22870330, 2012). "Furthermore, VCP is involved in multiple disease states, including neurodegenerative diseases, and several tumor types, such as squamous cell carcinoma, prostate cancer, esophageal cancer, and colorectal tumors." (PMID 39489738, 2024). "Furthermore, synthetic androgen treatment downregulated SVIP levels but upregulated other ERAD components, including gp78, p97/VCP, and Derlin1, enhancing ERAD proteolytic activity both in glioma and prostate cancer cells." (PMID 37408196, 2023). "However, serum VCP levels were not meaningfully increased in patients with lung or prostate cancer." (PMID 22870330, 2012).
esophageal cancer (9 papers, 2012 to 2024). A primary or metastatic malignant neoplasm involving the esophagus. "It has been shown that miR-129-5p was deregulated in several tumor types including endometrial cancer, esophageal cancer, colon cancer and bladder cancer, and its verified target genes included SOX4, VCP/p97 and Cdk6." (PMID 24358111, 2013). "Similarly, the correlation between increased VCP expression and poor prognosis has also been observed in NSCLC, esophageal carcinoma, and colorectal tumors." (PMID 35562734, 2022).
Parkinsonism (9 papers, 2012 to 2026). Characteristic neurologic anomaly resulting from degeneration of dopamine-generating cells in the substantia nigra, a region of the midbrain, characterized clinically by shaking, rigidity, slowness of movement and difficulty with walking and gait. "Although VCP mutations were not linked to parkinsonism (due to lack of pathogenic variants) in a large cohort of patients, reduced VCP expression is observed in a small cohort of PD patients and in the N-methyl-4-phenyl-1,2,3,6-tetrahydropyridine/MPTP mouse model of PD." (PMID 41277110, 2026).
tauopathy (9 papers, 2022 to 2025). Neurodegenerative disorders involving deposition of abnormal tau protein isoforms (tau proteins) in neurons and glial cells in the brain. "Dysregulation of these quality control pathways is likely contributing to tauopathy pathogenesis, as exemplified by autosomal dominant pathogenic variants in VCP, a key proteostasis factor, which causes vacuolar tauopathy." (PMID 37832941, 2024). "However, in this case the disease-causing VCP mutation p.Asp395Gly is linked to the aggregation propensity of TAU, as it impairs the TAU disaggregase activity of VCP, making it a potential new therapeutic target for AD and other tauopathies." (PMID 38554150, 2024).
Huntington disease (8 papers, 2014 to 2023). Huntington disease (HD) is a rare neurodegenerative disorder of the central nervous system characterized by unwanted choreatic movements, behavioral and psychiatric disturbances and dementia. "Mutations on VCP have been linked to several forms of neurodegenerative disorders and endogenous VCP associates with protein inclusions in both Huntington’s disease and Lewy body dementia." (PMID 35517053, 2022). "Within this scope, mitochondrial localization of valosin-containing protein drives hyperactivation of mitophagy and leads to neurodegeneration in Huntington’s disease." (PMID 29951054, 2018).
multiple myeloma (8 papers, 2015 to 2025). "Preclinical studies on the orally bioavailable VCP/p97 inhibitor CB-5083 have demonstrated robust activity in highly secretory myeloma cells and several in vivo MM models." (PMID 40418254, 2025). "The VCP/p97 ATPase inhibitor OSSL_325096 induced apoptosis in MM cell lines, including BTZ-resistant cells, and in patient-derived primary myeloma cells via ER stress and associated signaling." (PMID 40418254, 2025). "Previous studies have indicated that VCP inhibition decreased the survival of multiple cancer cell lines: CB-5083 has been reported to diminish cell survival of human multiple myeloma, human acute lymphoblastic leukemia and human mantle cell lymphoma." (PMID 35385564, 2022). "We found that VCP/p97 was tied to multiple metabolic processes on the gene expression level in a diverse range of cancer cell lines and in patient-derived multiple myeloma cells." (PMID 30626938, 2019). "We found that pharmacological depletion of VCP enzymatic activity with mechanistically different inhibitors robustly induced proteotoxic stress in solid cancer and multiple myeloma cells, including cells that were insensitive, adapted, or clinically resistant to proteasome inhibition." (PMID 26720340, 2015). "This suggests that whilst VCP/p97 inhibition did not affect the amount of mineral produced by hMSC, proteasome inhibition subtly enhanced it, a finding compatible with reports of the anabolic effects of proteasome inhibitors on bone [39,], particularly in multiple myeloma." (PMID 30153561, 2018).
Cognitive impairment (7 papers, 2022 to 2025). Abnormal cognition is characterized by deficits in thinking, reasoning, or remembering. "Our findings also suggest that VCP structural variation might be a marker for cognitive impairment and ALS-FTD, supporting previous work showing an association of common variation in the VCP gene with FTD and cognitive impairment." (PMID 35091648, 2022). "However, it is important to mention that the results from patients with PSEN1, SQSTM1, VCP, and ANXA11 mutations highlight distinct patterns of cognitive impairment, reflecting both shared and gene-specific features of neurodegeneration." (PMID 40649976, 2025).
familial amyotrophic lateral sclerosis (7 papers, 2012 to 2022). An instance of amyotrophic lateral sclerosis that is caused by an inherited modification of the individual's genome. "Inclusion body myopathy associated with Paget's disease of bone and Frontotemporal dementia (IBMPFD) and 2% of familial amyotrophic lateral sclerosis (fALS) cases are caused by mutations in the valosin containing protein (VCP)." (PMID 24130765, 2013).
heart failure (7 papers, 2016 to 2024). Inability of the heart to pump blood at an adequate rate to meet tissue metabolic requirements. "Summary of current thinking: VCP/p97 deficiency damages myocardial fibers and induce heart failure, while VCP/p97 overexpression improves ischemia–reperfusion injury and pressure overload induced cardiac hypertrophy." (PMID 33439255, 2021). "They suggest the fly heart may serve as a unique system to investigate MSP-associated heart failure precipitated by VCP mutations." (PMID 27500162, 2016). "Overall, our findings shed light on the essential role of VCP in the heart under physiological conditions, providing new insights into molecular mechanisms in the development of heart failure." (PMID 38928151, 2024). "Our results reveal that homozygous KO mice are embryonically lethal, whereas heterozygous KO mice with a reduction in VCP by ~40% in the heart are viable at birth but progressively develop heart failure and succumb to mortality at the age of 10 to 12 months." (PMID 38928151, 2024). "Our previous studies demonstrated a strong link between the down-regulation of VCP expression and cardiomyocyte hypertrophy and heart failure under pressure-overload stress." (PMID 34831118, 2021). "Reciprocally, cardiac-specific overexpressing VCP protects mouse hearts against pressure-overload-induced pathological hypertrophy and heart failure, and it also protects against stress-induced cardiomyocyte death in vitro and reduced ischemic injury in vivo." (PMID 34831118, 2021). "Given the strong link between the pressure overload-induced cardiac hypertrophy and heart failure, we focused on the cardiac transcriptomic characterization of VCP in response to 2W TAC." (PMID 33093614, 2020). "Interestingly, cardiac-specific overexpression of wild-type VCP protected mouse hearts against pressure-overload-induced pathological hypertrophy and heart failure, substantiating the critical role of VCP in the heart." (PMID 35743185, 2022). "Recent studies also showed that deficiency of a valosin-containing protein (VCP) in the heart is associated with the pressure overload-induced pathologic cardiac hypertrophy and heart failure, likely through a mechanism by the activation of oxidative stress and the increased ROS production." (PMID 33920673, 2021). "Thus, such perturbations between VCP and cardiomyocyte-specific binding partners are likely triggers for cardiac dysfunction and heart failure, in patients." (PMID 27500162, 2016).
acute myeloid leukemia (6 papers, 2021 to 2025). Acute myeloid leukemia (AML) is a group of neoplasms arising from precursor cells committed to the myeloid cell-line differentiation. "VCP is a homohexameric ATPase that has been targeted for the treatment of multiple diseases including acute myeloid leukemia." (PMID 39746958, 2025). "CB-5339, a VCP inhibitor has proven to be the most promising as it is currently in phase I clinical trials for acute myeloid leukemia and myelodysplastic syndrome." (PMID 40612269, 2025). "To assess the short-term effects of VCP inhibition, we treated acute myeloid leukemia (AML) cells with the VCP inhibitors NMS-873 and CB-5083 as well as with the proteasome inhibitor MG-132 for 16 hours." (PMID 35385564, 2022). "In acute myeloid leukemia, inhibition of VCP promotes apoptosis via increased ubiquitination of proteasome components, autophagy-related proteins, and DNA damage response factors, impairs colony formation in malignant cells in vitro, while decreases disease load and prolonged survival of mice." (PMID 38777147, 2024). "Excitingly, a highly potent and selective ATP-competitive VCP inhibitor named CB-5339 is currently being evaluated in phase I clinical trials for acute myeloid leukemia (AML) and myelodysplastic syndromes (MDS) and is anticipated to enter clinical testing for solid tumors as well." (PMID 34680224, 2021).
cervical cancer (6 papers, 2016 to 2025). A primary or metastatic malignant neoplasm involving the cervix. "Of TLS genes, increased expression of SPRTN, DTL, POLD1, PCNA, and VCP occurred most often in cervical cancers." (PMID 36266721, 2022). "Valosin-containing protein (VCP) is a potential biomarker for the early detection of cervical cancer, is related to HPV transformation." (PMID 35590912, 2022). "An enzyme-amplified signal was used to detect the selected protein marker, VCP, in three types of samples: purified VCP from cervical cancer tissues, HeLa-cell lysate, and cervical cancer tissue extracts." (PMID 26934314, 2016). "In this report, we have focused on VCP as a potential marker for early detection of cervical cancer." (PMID 26934314, 2016). "The proposed magnetic focus lateral flow sensor (mLFS) was implemented in detection of cervical cancer biomarker valosin-containing protein (VCP) as proof of concept with exceptional detection limits of 25 fg/mL with enhanced sensitivity of 106 fold improvement over conventional lateral flow assays." (PMID 32806676, 2020). "The results showed that Valosin-containing protein (VCP) was significantly expressed in CIN2/CIN3 and cervical cancer." (PMID 26934314, 2016). "Normal, CIN2/CIN3, and invasive cervical cancer tissue from 30 patients (10 in each group) were collected, washed, and homogenized; equal amounts of protein were loaded on SDS-PAGE and expression levels of VCP were determined by Western Blot." (PMID 26934314, 2016). "VCP-specific immunohistochemical staining (validated by a point-of-care technology) provided sensitive (93%) and specific (88%) identification of CIN2/CIN3+ and may serve as a critical biomarker for cervical-cancer screening." (PMID 26934314, 2016).
Charcot-Marie-Tooth disease (6 papers, 2017 to 2025). An inherited degenerative disorder involving the peripheral nerves. "For example, mutations in VCP can be variably associated with Charcot-Marie-Tooth disease (CMT), FTD, ALS, and/or inclusion body myopathy with early-onset Paget disease in different members of the same family." (PMID 38132285, 2023). "Finally, VCP disease mutants are associated with sporadic amyotrophic lateral sclerosis, and hereditary spastic paraplegia and Charcot-Marie-Tooth disease." (PMID 28322724, 2017). "For instance, the same mutations of the valosin-containing protein (VCP) gene and C9orf 72 appear to be present in individuals with ALS, FTD, and other neurological syndromes, and mutations in kinesin family member 5A (KIF5A) are associated with ALS and the Charcot-Marie-Tooth disease." (PMID 33854469, 2021).
hereditary spastic paraplegia (6 papers, 2012 to 2023). Hereditary spastic paraplegias (HSP) comprise a genetically and clinically heterogeneous group of neurodegenerative disorders characterized by progressive spasticity and hyperreflexia of the lower limbs. "VCP is also a candidate modifier gene for neurofibromatosis type 1, ALS-related motor neuron degeneration, and hereditary spastic paraplegia caused by atlastin mutations." (PMID 37545006, 2023).
inclusion body myopathy with Paget disease of bone and frontotemporal dementia (6 papers, 2012 to 2023). "In 2004, Kimonis and colleagues provided the first evidence that mutations in the VCP gene result in inclusion body myopathy with Paget disease of bone and frontotemporal dementia (IBMPFD), which is a multiple tissue disorder associated with myopathy, bony defects and dementia." (PMID 29310658, 2018). "A rare multisystem degenerative disorder, known as inclusion body myopathy Paget’s disease of the bone and frontotemporal dementia (IBMPFD), is caused by dominantly inherited missense mutations in the VCP gene encoding p97/VCP." (PMID 23226521, 2012). "Inclusion body myopathy with Paget disease of bone and frontotemporal dementia (IBMPFD), also known as VCP disease and multisystem proteinopathy (MPS I), is an autosomal dominant hereditary disorder caused by monoallelic variants in the valosin containing protein (VCP) gene on chromosome 9p13.3–12." (PMID 35841038, 2022).
liposarcoma (6 papers, 2012 to 2021). A usually painless malignant tumor that arises from adipose tissue. "Mutations in several genes are causative for FALS, including fused in sarcoma/translated in liposarcoma (FUS), superoxide dismutase-1 (SOD1), TAR DNA-binding protein (TARDBP), angiogenin (ANG), vesicle-associated membrane protein B (VAPB), optineurin (OPTN), and valosin-containing protein (VCP)." (PMID 23577159, 2013).
melanoma (6 papers, 2009 to 2025). A malignant, usually aggressive tumor composed of atypical, neoplastic melanocytes. "Rescue experiments reconstituting p97/VCP expression in melanoma cells resulted in enhanced Melan-A/MART-126-35 epitope recognition, underlining the in vivo functional relevance of our results." (PMID 27143649, 2016). "In support, our data demonstrate that re-expression of p97/VCP in Melan-A/MART-126-35 CTL-resistant melanoma cells completely restored immune recognition by Melan-A/MART-126-35 CTL." (PMID 27143649, 2016). "Indeed, VCP/p97 re-expression in resistant melanoma cells completely restored immune recognition by Melan-A/MART-126-35 CTLs." (PMID 34576340, 2021). "VCP's dysregulation might disrupt the delicate balance of EndMT, leading to impaired wound healing and potentially facilitating extravasation of CTCs, as observed in melanoma." (PMID 39802400, 2025). "In particular, the essential non-inducible ERAD component p97/VCP has been found to be down regulated in CTL-resistant melanoma cells." (PMID 27143649, 2016). "Importantly, the down-regulation of p97/VCP was observed in two independent melanoma cell lines, indicating that such effect was not cell line-specific but rather a more general phenomenon in response to CTL exposure." (PMID 27143649, 2016).